GSK3B (glycogen synthase kinase 3 beta)
Diseases named in the same sentence as GSK3B in open-access papers (continued):
Sharing a sentence is not in itself a finding about the gene and the disease.
glioma (continued). "Since GSK-3β is the initiation step of proteasome-dependent degradation of β-catenin, we also examined levels of β-catenin in glioma tissues." (PMID 26388612, 2015). "Another study reported sensitization of glioma cells to tamoxifen-induced apoptosis by Pl3-kinase inhibitor mediated via the GSK-3β/β-catenin signaling pathway." (PMID 25685660, 2015). "Treatment of glioma cells with MAZ51 resulted in increased levels of phosphorylated GSK3β through the activation of Akt, as well as increased levels of active RhoA." (PMID 25268128, 2014). "PI3K/Akt, and the Akt downstream target GSK3β, are important in regulating cell morphology and cell migration in several cell types, including glioma cells." (PMID 25268128, 2014). "Recently, it has been shown that inhibition of GSK3β promotes apoptosis in glioma cells and PDA cells, and sensitizes PANC-1 cells to gemcitabine." (PMID 23626687, 2013). "We reported here that the localized phosphorylation of GSK-3β at the Ser9 (pSer9-GSK-3β) was critical for glioma cell invasion." (PMID 24312592, 2013). "Collectively, our results supported that GSK-3 was important for glioma cell invasion and that localized regulation of GSK-3β was critical." (PMID 24312592, 2013). "Here, we reported that GSK-3β was involved in the formation of cell polarity to affect glioma cell invasion, and it was also important for EGF-stimulated glioma cell invasion." (PMID 24312592, 2013). "Our results indicated that GSK-3 was important for glioma cell invasion and localized inhibition of GSK-3β was critical for cell polarity formation." (PMID 24312592, 2013). "Collectively, these results supported that the localized GSK-3β inhibition was important for glioma cell invasion." (PMID 24312592, 2013). "Taken together, these results suggested that GSK-3α and -3β were important for EGF-induced glioma cell invasion, in which GSK-3β was specifically regulated in an asymmetric way." (PMID 24312592, 2013). "Interference with GSK3β activity by siRNA inhibits cell migration and induces apoptosis of glioma cells by activating c-Myc and inactivating nuclear factor-κB (NF-κB) activities." (PMID 22494416, 2012). "Specific pharmacologic GSK-3β inhibitors and siRNA knockdown of GSK-3β reduced glioma cell motility." (PMID 22046442, 2011). "CELSR2 knockdown inhibited Wnt/β-catenin signaling, and the effect could be reversed by activating β-catenin using GSK-3β inhibitor in glioma cells." (PMID 41184253, 2025). "In CELSR2 KD glioma cells, suppressing GSK-3β activation using inhibitors induced downregulation of phosphorylated β-catenin and upregulation of unphosphorylated β-catenin which subsequently activated nuclear transcription and cell proliferation as shown by EdU labeling and cell cycle analysis." (PMID 41184253, 2025). "Moreover, the inhibition of GSK-3β with small molecules has been demonstrated to enhance the effect of TMZ in glioma cells and to reduce GB growth in vivo." (PMID 40157890, 2025). "To further confirm whether CELSR2 is involved in the regulation of Wnt/β-catenin signaling pathway to influence proliferation and cell cycle of glioma cells, we used the GSK-3β inhibitor TWS119 to activate Wnt/β-catenin." (PMID 41184253, 2025). "Glioma cell culture study showed that CELSR2 KD induced an upregulation of total GSK-3β (phosphorylated protein decrease) and phosphorylated β-catenin (total protein decrease), and a decrease of TCF/LEF activity, showing an inactive state of the Wnt-β-catenin signaling." (PMID 41184253, 2025). "Likewise, emerging evidence suggests that GSK-3β functions as a tumor promoter in glioma, playing a key role in proliferation, resistance to radio-chemotherapy, and activation of invasion." (PMID 40157890, 2025). "In vitro research has shown that caffeine may suppress the proliferation of glioma cells via the PKA/GSK3β pathways and inhibit cellular migration through the ROCK-FAK pathway." (PMID 39737152, 2024).
glioma (continued). "Likewise, in the comparison of the control and the CP group, the significantly upregulated LRATD2 is the main inducer of neuroendocrine tumor, which induces glioma by the cell cycle or Akt/GSK-3β/βpathways." (PMID 38891594, 2024). "Moreover, GSK3β participates in cellular proliferation and survival by activating nuclear factor κB-dependent gene transcription, suggesting an active role of GSK3β in tumorigenesis in pancreatic, colorectal, and prostate cancers, and gliomas." (PMID 36836894, 2023). "In glioma cells (H4) and in phaeochromocytoma-differentiated neurons (PC12), GSK3b inhibition using lithium chloride (LiCl) causes an increase in expression of PGC-1a1 and PGC-1a4 isoforms, but neither cell type expresses the B1E2 isoform which is the dominant form of PGC-1a in primary neurons." (PMID 37808866, 2023). "IFI30‐mediated EGFR/AKT/GSK3β/β‐catenin signaling not only promotes the epithelial–mesenchymal transition‐like phenotype by upregulating the expression of Slug, but also subsequently enhanced invasion and chemoresistance of glioma cells." (PMID 37408388, 2023). "In addition, IFI30 promoted the EMT‐like process in gliomas via the EGFR/AKT/GSK3β/β‐catenin signaling pathway both in vitro and in vivo." (PMID 37408388, 2023). "In addition, MALAT1 downregulates miR-101, consequently increasing resistance to TMZ in glioma cells by increasing glycogen synthase kinase 3β (GSK-3β) levels." (PMID 36819921, 2023). "Our results revealed that quercetin decreased the expression of ZEB1 and this effect could be rescued by SB216763, implying that quercetin decreases ZEB1 expression via GSK-3β/β-catenin axis in glioma." (PMID 36386155, 2022). "Moreover, the authors demonstrated that the degree of GSK3β inhibition was inversely correlated with the degree of invasion, suggesting that GSK3β inhibition directly impacts cytoskeleton-regulated migration of glioma cells." (PMID 36358803, 2022). "The effect of immunohistochemical markers of gliomas on GSK3β activity was revealed." (PMID 35625744, 2022). "It was also found in vitro that lBX2.AS1 silencing could activate Akt/GSK3β pathway to inhibit the proliferation and metabolism of glioma cells." (PMID 36033510, 2022). "Taken together, lnc-ZNF281 inhibits glioma cell proliferation and migration via AKT/GSK-3β/β-catenin pathway and may serve as a potential target for glioma treatment." (PMID 34056009, 2021). "Moreover, knockdown of GSK-3β induced c-Myc-dependent cell death and promoted glioma stem cell proliferation and colony formation." (PMID 34887392, 2021). "Moreover, MYH9 binds to GSK-3β and promotes its ubiquitinated degradation, resulting in the promotion of malignant phenotypes and chemotherapy-resistant of glioma cells." (PMID 34887392, 2021). "We wonder that whether lnc-ZNF281 suppressed the progression of glioma by AKT/GSK-3β/β-catenin pathway." (PMID 34056009, 2021). "Besides, overexpression of lnc-ZNF281 in glioma cells inactivated the AKT/GSK-3β/β-catenin signaling pathway." (PMID 34056009, 2021). "Moreover, in a cultured glioma cell line U-251, GSK3β was shown to interact with Akt and snail and CUX1 pathway and regulate ionizing radiation-induced epithelial-mesenchymal transition as well as migration and invasion." (PMID 34975828, 2021). "Herein, we reported for the first time that fractionated IR (fraction-dependent manner as to the clinical daily used dose: 2 Gy per day) induced GSCs with the stemness phenotype by p62-mediated autophagy through the Wnt/β-catenin/GSk3β/P62 axis signaling pathway in human glioma cells." (PMID 34069945, 2021). "Because of the role of lncRNA at transcriptional and post-transcriptional levels, GNG12-AS1 may regulate the transcription or translation ability of some genes which influence the AKT/GSK-3β/β-catenin pathway in glioma cells." (PMID 32735016, 2020). "Notably, the previous studies illustrated that Nobiletin and SCD1 regulate EMT of glioma cells via the Akt/GSK3β/β-catenin signaling axis." (PMID 32735016, 2020).
glioma (continued). "The KD of GSK3α in U87 glioma cells promotes hnRNPA1 stability and mRNA synthesis to upregulate splice variant expression of the anti-apoptotic proteins BIN-1 and Mcl-1 with the parallel repression of RON, while in GSK3β inhibition, the opposite effect occurs." (PMID 33339170, 2020). "Furthermore, we found that knockdown FTL dramatically repressed EMT and reduced migration and invasion of glioma by regulating AKT/GSK3β/ β-catenin signaling both in vitro and in vivo." (PMID 32677981, 2020). "Moreover, we found that miR-29s-induced TRAF4 knockdown markedly blocked the phosphorylation of AKT and GSK-3β as well as the expression of cyclin D1 and c-Myc in glioma cells." (PMID 30348972, 2018). "Mechanistically, FoxM1/ADAM17 axis activated the EGFR/AKT/GSK3β signaling pathway and ADAM17/EGFR/GSK3β axis could maintain FoxM1 stability in glioma cells." (PMID 29700308, 2018). "Whether over-expressed YAP competes with β-catenin for binding AXIN/APC/GSK3β complex and then releases β-catenin from the complex in glioma context?" (PMID 28962630, 2017). "A recent study revealed that GSK3β could inhibit glioma progression via regulation of mTOR/p70S6K1 signaling pathway." (PMID 27792996, 2016). "Also we observed that doxazosin cell cycle arrest and the decrease on proliferation of C6 and U138-MG glioma cells appears to be mediated by GSK-3β dephosphorylation/activation." (PMID 27123999, 2016). "Taken together, these findings suggest that p-GSK-3β (Ser9) may be a useful biomarker for glioma development, and provide new information for using GSK-3β-based diagnostics and/or potential therapeutic target for glioma treatments in the future." (PMID 26388612, 2015). "However, the role of GSK-3β and GSK-3β Ser9 phosphorylation in glioma development is unclear, and the mechanisms underlying GSK-3β regulation of neoplastic transformation and tumor development remains to be elucidated." (PMID 26388612, 2015). "However, the expression levels of p-GSK-3β (Ser9) were much higher in glioma tissues when compared to normal tissues, and were correlated with higher glioma grades." (PMID 26388612, 2015). "Considered together, our data suggest that the effects of MAZ51 in glioma cells could be mediated through phosphorylation of Akt/GSK3β and activation of RhoA." (PMID 25268128, 2014). "We here compared the migratory ability among glioma cells with up-regulated GSK3β activity by transfecting cells with wild-type or constitutively active forms of GSK3β, as well as down-regulated GSK3β activity by transfecting cells with inhibitory peptide GID5-6." (PMID 24312592, 2013). "In glioma cell lines, inhibition of GSK-3β by LiCl indeed increases proliferation." (PMID 23504389, 2013). "Our results suggested that targeting GSK-3β localization might be important for inhibition of glioma invasion." (PMID 24312592, 2013). "It has been reported that PKCζ, a main form of aPKC in glioma cells, could directly phosphorylate GSK-3β." (PMID 24312592, 2013). "We then investigated whether GSK-3 and asymmetric GSK-3β regulation were necessary for EGF-induced glioma cell invasion." (PMID 24312592, 2013). "Our understanding of the proteins that initiate, and the pathways that regulate, glioma invasion is continually expanding, such as the recent discovery that CD95 via the activation of the PI3K/Akt/glycogen synthetase kinase (GSK3β) pathway regulates glioma invasion." (PMID 19067488, 2008). "Therefore, we can hypothesize that GSK-3β might have opposing functions in the regulation of Gal9 in gliomas, which could depend on the status of PTEN." (PMID 40157890, 2025). "The upregulated YTHDF2 binds to the mRNA of the negative regulatory factors APC and GSK3β in the Wnt-β-Catenin pathway that are modified by m6A, promoting their degradation and thereby activating the Wnt-β-Catenin pathway, ultimately promoting glioma migration, invasion, and EMT." (PMID 38637831, 2024).
glioma (continued). "Moreover, GSK3β and GSK3α inhibition by lithium reduces migration and invasion of glioma cells." (PMID 36836894, 2023). "Also, increased GSK-3β expression might be associated with resistance to TMZ and poor prognosis in glioma patients by decreasing MGMT promoter methylation and thus upregulation of MGMT." (PMID 36819921, 2023). "Combined with our research, it is speculated that inhibiting the expression of FAM84B can affect the AKT/GSK-3β/β-catenin pathway to regulate the key proteins of the cell cycle, induce cell cycle arrest, and then inhibit the malignant proliferation of glioma cells." (PMID 36419094, 2022). "Thus, AEG-1 targets GSK-3β and activates Wnt/β-catenin signaling in glioma cells." (PMID 34462446, 2021). "Moreover, we revealed that lnc-ZNF281 might inhibit proliferation and migration in glioma via AKT/GSK-3β/β-catenin signaling pathway." (PMID 34056009, 2021). "Besides, EMT pathways could cross talk with the PI3K/Akt/GSK3β pathway in glioma, through HIF-1α, PTEN, and the WNT/β-catenin pathways." (PMID 33029523, 2020). "In addition, FoxM1 activated EGFR/AKT/GSK3β signaling pathway in glioma cells." (PMID 29700308, 2018). "However, the role and the molecular mechanism of GSK-3β in glioma still remain to be elucidated." (PMID 26388612, 2015). "The lack of inhibition of VPA-mediated GSK3β in glioma cells could be associated with the differential VPA sensitivity and radiation response of cancer cells." (PMID 26413814, 2015). "GSK3β may therefore be an important therapeutic target for gliomas." (PMID 26437223, 2015). "Thus, we examined whether MAZ51 could influence Akt phosphorylation status and the activation or inactivation profiles of GSK3β in C6 glioma cells." (PMID 25268128, 2014). "In addition, lithium can reduce the invasiveness of glioma cells, and this effect may be related to GSK3β." (PMID 24618715, 2014). "Therefore as the asymmetric distribution of GSK-3β was disrupted by uniform inhibition or activation, glioma cell invasion could be inhibited." (PMID 24312592, 2013). "We thus asked whether the GSK-3β-dependent cell polarity was important for glioma cell invasion." (PMID 24312592, 2013). "The inactivation of GSK-3β facilitates the accumulation of β-catenin in the nucleus, where it promotes EMT and enhances glioma cell proliferation and invasion." (PMID 41141394, 2026). "Simultaneously, WNT3A-induced activation of the GSK-3β/β-catenin signaling and enhancement of cell cycle was significantly compromised in cultured CELSR2 KD glioma cells." (PMID 41184253, 2025). "In human gliomas, YAP suppresses glycogen synthase kinase 3 beta (GSK3β) activity, leading to increase the protein level and activity of β-catenin, which drives glioma cell proliferation." (PMID 40673277, 2025). "Our study demonstrates that GSK-3β and β-catenin are the downstream signaling partners of CELSR2 in regulating human glioma growth." (PMID 41184253, 2025). "Ferritin upregulation is associated with the epithelial-mesenchymal transition (EMT) and chemoresistance in glioma under hypoxic conditions, by activating the AKT/Glycogen synthase kinase-3 beta (GSK3β)/β-catenin signalling pathway." (PMID 40078366, 2025). "Consistently, the hyperphosphorylation of microtubule‐associated proteins (MAP2 and MAP1B) revealed the activation of CAMK2G, GSK3A, GSK3B, MAPK8, and MAP4K6, corresponding to the active MAPK signaling pathway in glioma." (PMID 39716938, 2025). "In U251 glioma cells, HERV-W env overexpression upregulated BDNF via glycogen synthase kinase 3 beta(GSK3β) Ser9 phosphorylation." (PMID 41200560, 2025).
glioma (continued). "In our study, we are the first to demonstrate in glioma cells that YTHDF2 binds to m6A -modified APC and GSK3β mRNA, promoting their degradation and thereby activating the Wnt-β-Catenin pathway." (PMID 38637831, 2024). "DYRK2 is expressed in human tumors and can suppress glioma cell migration, affecting E-cadherin and vimentin expression in the PI3K/AKT/GSK3β signaling pathway." (PMID 38584840, 2024). "While our study did not explore the overall impact of PRMT6 on m6A modifications in glioma cells, we found that PRMT6 affects the m6A modification of APC and GSK3β mRNA, as overexpression of PRMT6 reduces the m6A levels on these mRNAs." (PMID 38637831, 2024). "We further demonstrated that the EGFR/AKT/GSK3β/β‐catenin axis played a role in IFI30‐promoted the EMT‐like phenotype, which is a well‐recognized mechanism in the diffuse infiltration of glioma cells." (PMID 37408388, 2023). "U87 and U251 glioma cells upon pcDNA3.1‐SFRP1 treatment was found to have elevated SFRP1 and E‐cadherin expression and reduced p‐GSK‐3β, β‐catenin, N‐cadherin, Vimentin, and Snail expression, with no change in GSK‐3β expression." (PMID 36756719, 2023). "Immunohistochemical staining results of 125 brain tissue samples showed that the expression trends of ZDHHC4, p-GSK3β (Y216), and p-STAT3 (Y705) were consistent and positively correlated with the pathological grade of glioma." (PMID 35606353, 2022). "WBSCR22 enhances glioma cell growth and metastasis by regulating the PI3K/AKT/GSK3β signaling pathway." (PMID 35590385, 2022). "The potential therapeutic mechanism of miR‐29a/b/c in glioma is to inhibit tumor cell proliferation by downregulating cyclin D1 expression, phosphorylation of AKT, GSK‐3β, and thus inducing G1 blockade." (PMID 37786890, 2022). "Here, we found that lnc-ZNF281 suppressed glioma cell proliferation and migration and downregulated AKT/GSK-3β/β-catenin signaling pathway." (PMID 34056009, 2021). "The expression levels of Wnt-related genes, including β-catenin, GSK-3β, cyclin D1, and CD44 were all decreased in AEG-1 knockdown glioma cells compared to that in the control cells." (PMID 34462446, 2021). "These mast cells reduce the proliferative and invasive capacity of glioma cells and induce their differentiation by depleting the potency of glioma stem cells, possibly by inactivating the STAT3-mediated pathway through GSK3β downregulation." (PMID 34629960, 2021). "The Kruskal–Wallis test confirmed a significant difference in methylation of all examined genes between glioma types (p < 0.001 for AKT1, AKT3, CHUK, GSK3β, EGFR, PTEN, PIK3AP1; p = 0.032 for AKT2)." (PMID 34209611, 2021). "The silence of GNG12-AS1 inhibited the proliferation, migration and epithelial–mesenchymal transition of glioma cells, and reduced the activity of the AKT/GSK-3β/β-catenin pathway." (PMID 32735016, 2020). "Using IM-12 or CTNNB1 plasmid significant reversed the oncogenic function of FTL in mediating EMT in glioma, which strongly indicated that FTL promoted EMT by regulating AKT/GSK3β/ β-catenin signaling." (PMID 32677981, 2020). "From the score we can see that the expression level of CKIP-1 in glioma tissues is lower than that in normal brain tissues, and the activation level of AKT/GSK3β/β-catenin signaling pathway is significantly higher than that in normal brain tissues." (PMID 31355268, 2019). "This also indicates that CKIP-1 is inhibited in glioma tissues, while the AKT/GSK3β/β-catenin signaling pathway is significantly activated." (PMID 31355268, 2019). "In order to further confirm that the role of UCA1 in glioma cell invasion and migration involved in Wnt/β-catenin signaling, we treated the U87 and SHG139 cells with both UCA1 siRNA and LiCl (GSK3β inhibitor, which activates the Wnt/β-catenin signaling)." (PMID 31596734, 2019).